HNRNPA1 (heterogeneous nuclear ribonucleoprotein A1)
Diseases named in the same sentence as HNRNPA1 in open-access papers (continued):
Sharing a sentence is not in itself a finding about the gene and the disease.
cancer (continued). "Overexpressed hnRNPA1 represses the splicing of PKM1 and promotes the expression of PKM2 isoform to facilitate the switch of cancer cells to anaerobic glycolysis." (PMID 37296881, 2023). "Given that HNRNPA1 and IGF2BP2 have been widely discovered to be able to regulate the progression of various cancers, including HCC, these two candidate RBPs were selected to engage in the following experiments." (PMID 35173610, 2021). "This study describes a cancer-specific isoform switch for a versatile RNA binding protein (RBP), HNRNPA1." (PMID 34961772, 2021). "Among these proteins, heterogeneous nuclear ribonucleoprotein A1 (hnRNPA1) modulates pyruvate kinase M (PKM) splicing, thereby affecting cancer metabolic reprogramming, such as aerobic glycolysis, and was therefore selected for further study." (PMID 33088214, 2020). "The TMPRSS2:ERG status was available from 6196 cancers (using ERG break apart FISH analysis) and from 11,521 cancers (using ERG-IHC) of all tumors with interpretable data on hnRNPA1." (PMID 32417965, 2020). "Silencing of HNRNPA1 or NCL in HCC cells using small RNA fragments (i.e., Aptamer BC15 for HNRNPA1 or AS1411 and AGRO100 for NCL) results in a potent reduction of cancer cell growth." (PMID 32932781, 2020). "It has been previously reported that hnRNPA1 is involved in the variable splicing of PKM mRNA, the upregulation of the ratio of PKM2/PKM1, and the promotion of cancer through aerobic glycolysis, which can be explained through the Warburg effect." (PMID 32296635, 2020). "High hnRNPA1 expression proved to be an independent prognostic parameter in all scenarios, however, limited to the subset of ERG-negative cancers." (PMID 32417965, 2020). "We also collected primary CAFs isolated from mouse tumors, and it is clearly shown that knockdown of USP7 decreased hnRNPA1 protein levels; and the suppression of each of the three genes in CAFs lead to ALOX15 up-regulation in cancer cells." (PMID 32106859, 2020). "Treatment of cisplatin relatively promoted the expression of USP7/hnRNPA1 in CAFs, as well as ALOX15 in cancer cells, but the mRNA of ALOX15 remained little changed." (PMID 32106859, 2020). "Together, these results demonstrate that Quercetin enhances the efficacy of BET inhibitors by suppressing hnRNPA1, and identify combination therapy with Quercetin and BET inhibitors for the treatment of cancer patients." (PMID 31480735, 2019). "hnRNPA1 knockdown and JQ1 treatment suppressed Survivin in cancer cells, which was validated by western blot analysis." (PMID 31480735, 2019). "An increasing number of targets, including RBPs such as HuR, hnRNPA1, IGFBP3, Sam68, DDX3, DHX9, and MBNL2, are under evaluation for the development of new cancer treatments." (PMID 29495341, 2018). "In the ASF-4-1 cell line as a normal cell, the expression levels of PTBP1, hnRNPA1, and SRSF3 were lower than those of all cancer cell lines tested." (PMID 30279379, 2018). "Our findings indicate that the PKM splicers of PTBP1, hnRNPA1, and SRSF3 were involved in the maintenance of cancer-specific metabolism and also tumorigenesis." (PMID 30279379, 2018). "On the other hand, in all cancer cell lines tested and in human fibroblast ASF-4-1 cell line, PTBP1 was fairly expressed, and good expression of hnRNPA1 and SRSF3 was observed in most of the cancer cell lines." (PMID 30279379, 2018). "Extranuclear distributions of HNRNPA1 and SRSF6 (cytosol/microsome) differed from those of other SRSFs (membrane/organelle) in both cancers." (PMID 27282379, 2016). "The UIs of CEA were >50 % in both cancers; it was also lower in GC (53 %) compared with CRC (92 %), and the results were similar to HNRNPA1 values." (PMID 27282379, 2016). "HNRNPA1 and SRSF6 in both cancers frequently (≥50 %) showed different distribution patterns from those of the other SFs." (PMID 27282379, 2016). "Splicing repressors hnRNPA1 and hnRNPA2 have been found to regulate PKM alternative splicing in cancer cells." (PMID 28105922, 2016).
cancer (continued). "Among genes downregulated by clofibrate, the major part belonged mainly to functional groups: “cancer” (STIP1, HNRNPA1, VIL1, and CDH1) and “cellular assembly and organization” (CLASP1 and MACF1)." (PMID 22619672, 2012). "The downregulated genes belonged mainly to the “cancer” biofunction (RPS27A, HNRNPA1, STIP1, and TFDP1)." (PMID 22619672, 2012). "Simultaneous PP2A activation and importin inhibition reduces nuclear levels of proteins that drive cancer progression and therapeutic resistance such as JUN, YAP, MYC, androgen receptor, hnRNPA1, and NF-κB under conditions where compounds that target PP2A or KPNB1 individually are inactive." (PMID 40588551, 2025). "For instance, as mentioned in the introduction, KHSRP interacts with hnRNPA1, a protein known to resolve G4 structures at telomeres and in the promoters of genes such as KRAS and TRA2B, thereby modulating their transcription in cancer cells." (PMID 39763191, 2025). "HNRNPA1 has been shown to facilitate the excision of exon 9 from the PKM pre-mRNA, thereby selectively inducing the formation of the oncogenic PKM2 isoform, a key determinant of the Warburg effect that promotes aerobic glycolysis and cancer cell survival." (PMID 39341825, 2024). "MYC is an essential molecular hub in CML pathophysiology and could actively participate in the dysregulation of PTBP1 and hnRNPA1 as well as PRMT5 and SRSF1, genes deregulated by MYC in other cancers." (PMID 36230624, 2022). "In FHC cells, the interaction between hnRNPK and hnRNPA1/R/U proteins was observed, which revealed that the hnRNPK/A1/R/U interaction was not specific to cancer cells." (PMID 35875075, 2022). "In particular, they are abnormally expressed in various types of tumors such as small cell lung cancer and gastric cancer, and knockdown of HNRNPA1 or the use of adapters targeting HNRNPA2 can inhibit cancer cell proliferation, suggesting potential targets for cancer treatment." (PMID 33907500, 2021). "In addition, knocking out HnRNPA1 can enhance the inhibiting effect of JQ1 on expression of survivin and the sphere-forming ability of cancer cells, which is consistent with the effects of quercetin." (PMID 34235089, 2021). "In particular, the PRMT4-, 5-, and 7-mediated methylation of splicing factors, such as hnRNPA1, plays non-redundant roles in RNA alternative splicing regulation, and such a mechanism was demonstrated to be potentially important for cancer development." (PMID 33782401, 2021). "That hnRNPA1 expression provided additional prognostic information in patients with Gleason score 4 + 3 cancers, but not in any patient subsets with an identical quantitative Gleason score, demonstrates the power of the quantitative Gleason scoring approach." (PMID 32417965, 2020). "The limitation of the prognostic impact of hnRNPA1 to a molecular subgroup such as ERG-negative cancers is not an exception." (PMID 32417965, 2020). "Supportive of this, the cancer genes HNRNPA1 and STRAP exhibit high expression in diverse cancers." (PMID 32634135, 2020). "The average Ki67LI increased from 1.06 ± 0.1 in cancers with lacking hnRNPA1 expression to 3.15 ± 0.06 in cancers with strong hnRNPA1 (p < 0.0001)." (PMID 32417965, 2020). "Importantly, cisplatin and paclitaxel promote miR-522 secretion from CAFs by activating USP7/hnRNPA1 axis, leading to ALOX15 suppression and decreased lipid-ROS accumulation in cancer cells, and ultimately result in decreased chemo-sensitivity." (PMID 32106859, 2020). "Alternatively, it cannot be excluded that our IHC protocol was not optimally suited to reveal hnRNPA1’s prognostic value specifically in the subset of ERG-positive cancers." (PMID 32417965, 2020). "In these tumors, hnRNPA1 was so much upregulated that hnRNPA1-negative or weak cancers were virtually absent." (PMID 32417965, 2020). "Importantly, hnRNPA1 knockdown also enhanced the effects of the BET inhibitor OTX-015 at inducing apoptosis and suppressing proliferation of cancer cells." (PMID 31480735, 2019).
cancer (continued). "Our results strongly suggest that PTBP1, hnRNPA1, and SRSF3 controlled cancer-specific energy metabolism at least in part through affecting the PKM gene expression profile via AS, which was clarified by RIP and IP assays, and that these proteins coding RNA would be targets for RNA medicine." (PMID 30279379, 2018). "Our previous study indicated that splicing factor hnRNPA1 could bind to the human homologue of mouse double minute (MDM2), an oncogene which has been observed to be over-expressed in numerous types of cancers." (PMID 28035066, 2017). "Therefore, HNRNPA1 and SERPINE1 as hub proteins are involved in cancer and also ethanol consumption; they can be candidate for more investigations." (PMID 28228815, 2016). "hnRNPA1 also appeared upregulated in primary carcinoma samples from patients with metastasis, but not significantly." (PMID 26791953, 2016). "For the expression ratio between HP1α-V3 and hnRNPA1, we observed an increase between normal breast tissue and primary carcinoma samples both from patients without metastasis (1.46-fold, P < 0.0001) and patients with metastasis (1.79-fold, P < 0.0001)." (PMID 26791953, 2016). "For hnRNPA1 mRNA we observed an increased expression between normal breast tissue and primary carcinoma samples from patients without metastasis (1.33-fold, P < 0.01)." (PMID 26791953, 2016). "When HNRNPA1 and SRSF6 were upregulated in whole cancer-cell lysates, they were predominantly distributed in nuclear and/or cytosol/microsome fractions; the upregulated SFs in the cytosol/microsome fraction were detectable in >50 % of upregulated cases in both cancers." (PMID 27282379, 2016). "However, extended analyses in subsets of cancers defined identical classical and quantitative Gleason scores further revealed that hnRNPA1 provided additional prognostic information in Gleason 4 + 3 cancers (p = 0.0004) but not in cancers with an identical quantitative Gleason score." (PMID 32417965, 2020). "In the present study, we revealed that hnRNPA1 specifically bound miR-196a through a specific sequence (UAGGUA) on the 5′ end of miR-196a, directed miR-196a packaging into exosomes, which might provide a mechanism for eliminating miR-196a in the HNC stroma niche during cancer therapy." (PMID 30642385, 2019). "We identified no significant correlated expression pattern between hnRNPA1 and CBX5 in the NCI-60 cancer cell panel." (PMID 26791953, 2016). "The complete lack of a prognostic value of hnRNPA1 in ERG-positive cancers, however, might suggest that ERG activation overrides the tumor-promoting function of hnRNPA1." (PMID 32417965, 2020).
tumor (89 papers, 2010 to 2026). "Our results so far indicated that HNRNPA1 lactylation fuels tumor growth, prompting us to investigate the underlying mechanisms." (PMID 41275207, 2025). "Enrichment analysis was performed to elucidate the mechanisms underlying the activation of anti-tumor immunity induced by HNRNPA1 knockdown." (PMID 38867190, 2024). "A strong association between hnRNPA1 upregulation and tumor cell proliferation that was independent from the Gleason score supports a role for tumor cell aggressiveness." (PMID 32417965, 2020). "Targeting HNRNPA1 can result in aberrant alternative splicing events and generation of immunogenic neoantigens that elicit anti-tumor immunity." (PMID 40046063, 2025). "In vivo, xenograft tumor models, both HNRNPA1 knockout and selective inhibition of K350 lactylation led to a substantial decrease in tumor growth, as evidenced by reduced tumor weight and volume." (PMID 41275207, 2025). "Polydatin also significantly inhibited tumor proliferation in vivo and and the PKM2 staining also indicate that polydatin can block variable shear event of PKM2 caused by HNRNPA1 lactylation, demonstrating its antitumor efficacy in BLCA." (PMID 41275207, 2025). "Downregulation of hnRNPA1 inhibits the NF-κB pathway, leading to reduced telomerase activation, unsustainable telomere length, and inhibition of tumor development." (PMID 39796281, 2025). "Previous research indicates that hnRNPA1 suppresses pro-apoptotic proteins, thereby influencing tumor growth." (PMID 39834948, 2024). "usp7 promotes the entry of CAF-derived miR522 into the exosome by stabilizing hnRNPA1 through deubiquitination, which regulates tumor progression through the usp7/hnRNPA1 axis." (PMID 39253578, 2024). "We analyzed hnRNPA1 expression in HCC tissues compared to non-tumor tissues using RNA-seq and immunohistochemistry." (PMID 39834948, 2024). "Taken together, these findings suggest that hnRNPA1 plays a different regulatory role and acts as a tumor suppressor gene in AGS and Kato III cells by regulating the formation of RONΔ160." (PMID 38268030, 2024). "Quercetin also enhanced the effectiveness of BET antagonists at reducing cellular proliferation and tumor development while decreasing hnRNPA1, which regulates the translation of mRNA." (PMID 38690008, 2024). "Mechanistically, we discover that ZMYND11 exhibits tumor suppressive roles by recognizing arginine-194-methylated HNRNPA1 dependent on its MYND domain, thereby retaining HNRNPA1 in the nucleus and preventing the formation of stress granules in the cytoplasm." (PMID 39341825, 2024). "Previous studies have shown that hnRNPA1 not only acts as a translational repressor of several genes to inhibit tumor progression but also directly controls the activity of splicing silencers to inhibit the occurrence of splicing events." (PMID 38268030, 2024). "Immunohistochemistry performed on HCC patient tissues validated the significant elevation of hnRNPA1 in tumor tissues compared to adjacent non-tumor tissues (p < 0.001)." (PMID 39834948, 2024). "Recent studies reported that USP7 acts as a co-activator in tumor initiation by stabilizing Axin and hnRNPA1." (PMID 36878903, 2023). "Meanwhile, moderate or strong heterogeneous nuclear ribonucleoprotein A1 (hnRNPA1) immunostaining was relevant to positive surgical margin and adverse tumor features." (PMID 37859989, 2023). "hnRNPA1 is one of the most abundant RNA binding proteins in the hnRNPs family, and its crucial function in tumor is particularly noticeable." (PMID 35814393, 2022). "It has been reported that hnRNPA1 can regulate tumor metastasis and EMT transition through a variety of different molecular mechanisms." (PMID 35814393, 2022). "HnRNPA1 has attracted significant attention as a promising tumor-related regulatory factors of alternative splicing." (PMID 35814393, 2022). "As an RNA-binding protein, hnRNPA1 can regulate the expression and translation of several mediators involved in tumour initiation and progression." (PMID 35814454, 2022).
tumor (continued). "According to these findings, they suggested that KMP suppresses glycolysis and tumor growth in CRC probably through the miR‐339‐5p‐hnRNPA1/PTBP1‐PKM2 axis, indicating a novel elucidation for the molecular aspects of the anticancer roles of KMP." (PMID 36259115, 2022). "We identified that hnRNPA1 loaded batched tumor-promoting miRNAs into sEVs with the assist of caveolin-1 (CAV1) in A549 cells." (PMID 34222256, 2021). "The knockdown of USP7, hnRNPA1, or lncFERO in GC cells relatively suppressed tumor growth in the saline groups, but remarkably increased chemosensitivity in the cisplatin groups." (PMID 34845198, 2021). "Along with high levels of methylation of PRMT4, PRMT5, PRMT7, and hnRNPA1 in tumor samples, changes in gene alternative splicing were observed, such as those for PPARA, SREBF2, RAB27B, and WDPCP in BRCA, CRC, and PC samples." (PMID 33782401, 2021). "Among normalized genes were Hnrnpa1 and Mbnl2 mRNA expression, whose expression was significantly increased in hearts during advanced tumor burden." (PMID 34669013, 2021). "BC15-31 is a DNA aptamer that targets heterogeneous nuclear ribonucleoprotein A1 (hnRNP A1), which plays a crucial role in the process of pre-RNA maturation and is also essential for the rapid proliferation of tumor cells." (PMID 34262898, 2021). "Three stable cell strains with knockdown of USP7, hnRNPA1, or lncFERO were constructed by using lent-viruses containing shRNAs, and then the cell strains were used for subcutaneous tumor implantation." (PMID 34845198, 2021). "In conclusion, our findings revealed powerful sEV-miRNA loading ability of hnRNPA1, which mediates the encapsulation of batched tumor-promoting sEV-miRNAs." (PMID 34222256, 2021). "And USP7 promotes the packaging of lncFERO into exosomes from GC cells through regulating deubiquitination on hnRNPA1, which ultimately leads to chemo-resistance and tumor progression through the exo-lncFERO/hnRNPA1/SCD1 axis." (PMID 34845198, 2021). "We also compared the expression level of these SFs in GBM tumor tissues and adjacent normal tissues and found that 7 factors were significantly dysregulated, including HNRNPA1, HNRNPC, HNRPLL, NOVA1, SF3B1, KHDRBS2, and TIA1." (PMID 34326872, 2021). "The knockdown of USP7, hnRNPA1 or miR-522 in CAFs observably suppressed tumor growth and enhanced sensitivity to cisplatin, but up-regulated Lipid ROS levels in tumors." (PMID 32106859, 2020). "Direct comparison of the hnRNPA1 immunostaining intensity in normal and cancerous glands in the same tissue spot indicated that hnRNPA1 becomes upregulated during tumor development." (PMID 32417965, 2020). "Taken together, we provided in vivo evidence to demonstrate that USP7/hnRNPA1 promotes exo-miR-522 secretion from CAFs, decreasing lipid-ROS levels in tumors and facilitating tumor growth." (PMID 32106859, 2020). "The inhibited expression of USP7, hnRNPA1 and miR-522 prolonged the survival period of tumor-bearing mice, and the mice in the cisplatin groups had a better survival compared with mice treated with saline." (PMID 32106859, 2020). "Together with our findings, these data argue for a general role of hnRNPA1 for tumor cell aggressiveness." (PMID 32417965, 2020). "ALOX15, one of the key genes leading to ferroptosis, showed a sharp decrease, while the levels of USP7 and hnRNPA1 were clearly increased in tumor tissues." (PMID 32106859, 2020). "We found that hnRNPA1, a nuclear protein known to control mRNA export and mRNA translation of anti-apoptotic proteins, mediates some anti-tumor effects by Quercetin." (PMID 31480735, 2019). "The results of the xenograft assay revealed that the tumors formed by CAL 27 plus CAF-hnRNPA1 cells grew faster than those in the control group, and silencing hnRNPA1 expression in CAFs significantly reduced tumor growth." (PMID 30642385, 2019). "Significantly, we demonstrate that Quercetin decreases hnRNPA1 and enhances the anti-tumor effects of BET inhibitors in vivo." (PMID 31480735, 2019).